KRAS (KRas proto-oncogene, GTPase)
Diseases named in the same sentence as KRAS in open-access papers (continued):
Sharing a sentence is not in itself a finding about the gene and the disease.
tumor (continued). "CDK9 inhibitory activity was experimentally confirmed using LS513 (KRAS G12D), SW620 (KRAS G12V), and Colo320 (RAS WT) tumor cell line models, and demonstrated the effectiveness of this group of molecules in treating cancer harboring KRAS mutations." (PMID 37569406, 2023). "Inactivation of many tumor suppressor genes had strikingly different effects on the growth of BRAF-driven tumors compared to tumors driven by either KRAS variant." (PMID 37828026, 2023). "Tumor initiation in PDAC is predominantly caused by KRAS mutations, occurring in approximately 90% of patients." (PMID 37659057, 2023). "In the evaluation of patients with KRAS mutations in terms of tumor stage, the median stage of the wild-type patients was 4 (3‒4), and the median stage of the mutant-type patients was 4 (4‒4) (p = 0.601)." (PMID 37639911, 2023). "Radiomics is a non-invasive method that can help determine KRAS status by localizing the area of the tumor most likely to have a KRAS mutation and guiding the biopsy." (PMID 37626641, 2023). "HLL_gldm_SmallDendenceLowGrayLevelEmphasis) in the KRAS mutation group were higher than that in the wild-type group, which suggests more tumor heterogeneity in the tumor tissue in the ROI range." (PMID 37311935, 2023). "The G12D alteration was the most frequently observed KRAS mutation, accounting for 36.50% of tumor samples, while the G12V alteration was detected in 21.75% of analyzed tumor samples." (PMID 38201431, 2023). "Most are highly infiltrated by immune cells, but there are also MSI-H CRCs with low immune infiltration that are associated with mucinous histology, KRAS mutations and Wnt/Notch activation, greater tumor size, distant metastasis or early recurrence." (PMID 37492581, 2023). "Despite having no data until today on the 10 patients with PDAC enrolled in this trial, three out of seven patients with KRAS-mutated colorectal cancer with available tumor response evaluation achieved tumor reduction (all with stable disease by RECIST)." (PMID 37894382, 2023). "In detail, KRAS-mutated CRCs had a lower frequency in MSI-High (15% vs. 42%; p = 0.015) compared with KRAS-WT, though KRAS mutation was associated with higher tumor-cell turnover." (PMID 37298928, 2023). "The highest frequency of mutations detected was in the KRAS gene, in tumor biopsies and plasma samples, followed by mutations of the PIK3CA, NRAS and BRAF genes." (PMID 37176143, 2023). "The findings additionally suggest that tumor tissues harboring distinct KRAS mutations exhibit variations in immune cell composition." (PMID 37954616, 2023). "In an ongoing trial evaluating MEK inhibitor selumetinib in combination with olaparib in primarily KRAS-mutated tumours, 2 of 14 patients had a confirmed partial response, and the combination was safe and tolerable." (PMID 37430137, 2023). "On comprehensive genomic profiling, this tumor was KRAS wild-type, MS stable and featured a low TMB of 1 mutation/Mb." (PMID 37404765, 2023). "Meanwhile, among the 75 tumor samples with the KRAS G12D mutation detected at DNA level, 41 (55%) had protein evidence from the PepQuery2 analysis." (PMID 37072382, 2023). "Except for one tumor, all tumors with KRAS mutations had lower K20 prediction scores than KRAS WT tumors." (PMID 37141389, 2023). "Many studies have identified KRAS as a direct target of miR-134-3p, thereby causing its tumor-suppressive effect." (PMID 37409119, 2023). "Tumours demonstrating the MaP pattern of stromal invasion more frequently harboured core MAPK pathway mutations (KRAS, BRAF, NRAS)." (PMID 37169775, 2023). "Apart from the common tumor types, the landscape of the KRAS mutation in rare tumors is investigated, with an overall mutation rate of 8.7%; and G12D and G12V, along with G13D, are the most common subtypes." (PMID 36675641, 2023). "Among the 46 patients with a KRAS exon 2 mutated tumour, KRAS-mutated ctDNA was detected at baseline in 42 patients (91%)." (PMID 37947598, 2023).
tumor (continued). "KRAS mutations were detected in 45.2% of tumor samples, primarily in exon 2 (40.4%) and exon 3 (2.9%)." (PMID 37628868, 2023). "Collectively, these results indicate that PITPNC1 controls the expression of a gene signature with clinical implications for KRAS-mutated tumours." (PMID 37210549, 2023). "The model consists of ROS1 gene mutations, KRAS gene mutations, tumor staging, and endocrine system disease history, and has good predictive ability." (PMID 37468609, 2023). "YB-1 is constitutively phosphorylated at S102 in KRAS-mutated tumor cells, i.e., in CRC cells and in triple-negative breast cancer (TNBC) cells." (PMID 36313934, 2023). "Combination of oncolytic virotherapy with small molecules targeting the MEK-ERK pathway has also been shown to induce more profound antitumor efficacy than monotherapy in in vivo tumor models with KRAS/BRAF mutations." (PMID 37972012, 2023). "We explored the effects of a specific probiotic blend on PC mice xenografted with KRAS wild-type or KRASG12D mutated cell lines alone or together with gemcitabine+nab-paclitaxel treatment to then assess tumor volume and clinical pathological variables." (PMID 37019893, 2023). "In our hospital KRAS mutations are assayed only in Stage IV tumors and in patients with tumor recurrences, only if those patients are candidates to be treated with biologic agents." (PMID 37670964, 2023). "PIK3CA mutations are identified in 10–15% of metastatic CRC (mCRC) patients, and a recent meta-analysis suggested their association with proximal tumor location, mucinous histological subtype, and co-occurrence with KRAS mutations." (PMID 37628868, 2023). "In another recent study, cells developing resistance to the drug triplet maintained both the BRAF V600E mutation and KRAS mutation (G12D or G13D), demonstrating that the coexistence of both mutations confers greater treatment resistance to the tumor." (PMID 37958416, 2023). "When analyzed by ARMS-HRMA, the detection of KRAS mutations improved compared to that attained by direct sequencing in tumor and plasma samples, respectively." (PMID 37097304, 2023). "DDX3 not only promoted cell invasion in KRAS-mutated CRC cells, but also increased tumor aggressiveness and cetuximab resistance in KRAS-wild-type CRC, which was regulated by the YAP1/SIX2 axis." (PMID 38023215, 2023). "In the advanced pancreatic cancer, a decrease of KRAS mutant ctDNA identified an earlier tumor response to the therapy, and it is strongly associated with clinical outcomes than blood levels of tumor markers." (PMID 36937316, 2023). "All patients underwent tumor tissue biopsies to determine KRAS mutational status based on quantitative polymerase chain reaction and reverse hybridization from an accredited diagnostic laboratory at Jordan University Hospital." (PMID 36788889, 2023). "Mutation‐based analysis showed rapid clearance of KRAS from the circulation, consistent with tumor regression." (PMID 36468189, 2023).
tumor (continued). "Some studies investigated the tumour-informed approach through a specific gene mutational status (e.g., KRAS) and one study performed analyses with a patient-specific assay." (PMID 37947598, 2023). "Twenty-three patients had sufficient pre-treatment tumour tissue as well as plasma DNA available to identify and quantify KRAS mutations, 14 of the 23 (61%) patients had mutKRAS ctDNA detected (8 in the concomitant arm, 6 in the sequential arm)." (PMID 36813867, 2023). "KRAS gene mutations has been reported to be involved in the invasion and metastasis of tumor cells, as well as chemoresistance." (PMID 37035749, 2023). "KRAS mutations were noted in 13.04% (3/23) of CTCs, whereas 65.2% (15/23) showed KRAS mutations in matched primary tumours." (PMID 37761948, 2023). "This review intends to summarize the characteristics of KRAS mutations in solid tumors, update the latest clinical therapeutic strategies, and discuss the mechanisms of drug resistance and tumor development, as well as the immune microenvironment." (PMID 36675641, 2023). "In particular, treatment response differed for tumours classified as CMS4 by KRAS status, showing better response for cetuximab in KRAS wild-type and for bevacizumab in KRAS mutated tumours, respectively." (PMID 37666855, 2023). "The carcinogen AOM used in the present study induces DNA damage, leading to KRAS mutations and subsequent tumor development." (PMID 37834032, 2023). "We previously established and characterized an early-passage patient-derived LGSOC cell culture that reflects the molecular make-up of KRAS mutated LGSOC tumor." (PMID 37853495, 2023). "KRAS mutation was identified in the tumor of 137 patients (34.3%), and of these 53 (38.9%) were KRAS p.G12C." (PMID 37813923, 2023). "Elevated expression of VISTA on T cells, MDSCs and TAMs are associated with oncogenic KRAS-driven tumours and resistance to anti-PD-1 by ICB, identifying VISTA as a promising immunotherapy target." (PMID 36864508, 2023). "RMC-036 and RMC-037 have been developed to target the KRAS G12D mutations with promising in vivo results, inducing complete tumor regression of a KRAS G12D-mutated pancreatic xenograft." (PMID 37190303, 2023). "Combined MEK and SOS1 inhibition has also resulted in durable tumor regressions in KRAS mutation-driven cancer models." (PMID 37774394, 2023). "The relationship between KRAS-mutated tumor genomes and tumor inflammation predicted by the c-Score was also examined." (PMID 37558751, 2023). "Recently, it became clear that in the majority of Brown Tumours, hotspot somatic KRAS mutations are present." (PMID 37627135, 2023). "In this study, the ALK mutation group had higher edema/tumor ratio (5.66 ± 21.15) than KRAS (5.08 ± 8.70) and EGFR (2.38 ± 6.13) positive mutation groups, implicating worse survival in the ALK mutation group." (PMID 37508989, 2023). "KRAS G12C mutations are predominantly caused by smoking and are associated with a high-tumor mutational burden, which is predictive of response to ICB." (PMID 37581538, 2023). "Similar to Giant Cell Lesions, mutations in KRAS have been identified in Brown Tumours, which lead to MAPK/ERK activation." (PMID 37627135, 2023).
tumor (continued). "Overall, our results show that KRAS mutations, determined both in tumor tissue and in patient plasma, showed a significant adverse influence on OS in univariate analysis." (PMID 37176143, 2023). "In summary, we identified two TCRs specific for the KRAS-G12V-9 peptide and engineered TCR-T cells that displayed specific responses to varied tumor cells with the KRAS-G12V mutation." (PMID 37828002, 2023). "Anatomopathological analysis of the tumor is the gold standard for determining KRAS mutation, but it is an invasive test, and it only analyses a portion of the tumor." (PMID 37626641, 2023). "EMT was also linked to the tumor tissue specimen expression profile, together with KRAS signaling, myogenesis, apical junction components complex, coagulation and several immune-related pathways." (PMID 37082125, 2023). "Herein, we improved the detection efficiency and accuracy of multiplexed dPCR with melting curve analysis to detect KRAS mutations in circulating tumor DNA (ctDNA) prepared from clinical samples." (PMID 36810451, 2023). "Treatment with AMG-510 caused the regression of KRAS-G12C tumors and enhanced the anti-tumor efficacy of either chemotherapy or targeted drugs." (PMID 37110848, 2023). "The recently described involvement of KRAS mutations turned Brown Tumours from reactive lesions to potentially neoplastic lesions." (PMID 37627135, 2023). "Either the primary tumor or liver metastases can be tested for KRAS mutation analysis since there is a 96.4% concordance of mutational status between the primary sites and a metastasis." (PMID 36980565, 2023). "MRTX1133 has been shown to inhibit KRAS signaling in vitro and to cause tumor regression greater than 30% in PDX models." (PMID 37569406, 2023). "Our study aimed to evaluate the frequency of RAS, with a focus on KRAS variants, and their association with tumor location and some clinicopathological characteristics in Bulgarian CRC patients." (PMID 37628934, 2023). "In this case, we suppose that CNV, resulted from HERVs infection, was probably associated with the transformation to KRAS mutation-like state of tumor cell." (PMID 38097680, 2023). "Knockout or knockdown of KRAS G12S mutant allele inhibits proliferation of A549 cell line harboring the KRAS G12S mutation and tumor growth of xenograft models of A549 cells." (PMID 38188023, 2023). "The most successful of these has been the development of covalent allele-specific inhibitors that trap KRAS G12C in its inactive conformation and suppress tumour growth in patients." (PMID 37258666, 2023). "Accurately determining the tumor’s localization and KRAS mutational status is crucial for selecting the appropriate therapy and predicting the response to treatment." (PMID 37628934, 2023). "When comparing KRAS G12C mutant cases with the rest of the cohort, proximal tumours were less likely to carry the KRAS G12C mutation compared to distal tumours (OR 0.652, 95% CI 0.451–0.944, p = 0.024)." (PMID 37240418, 2023). "Activating mutations in the KRAS oncogene were observed in 92–95% of patients and constitute major steps in tumor initiation and progression." (PMID 37108468, 2023). "For example, the “apical junction” hallmark gene set was remarkably upregulated (P = 2.40E−16), whereas the “KRAS signaling up” hallmark gene set was significantly downregulated (P = 1.1E−3) in tumor samples." (PMID 36774361, 2023). "The pan-RAS inhibitor MCI-062 has been shown to exhibit anti-tumor and anti-KRAS activity in multiple mouse models of KRAS-mutated CRC." (PMID 37569406, 2023).
tumor (continued). "In 2019, it had already been reported that the loss of Atrx enhanced pancreatic injury and susceptibility to KRAS-mediated (M.K.Atrx) pancreatic damage in female mice, pioneering the attribution of anti-inflammatory and tumour-suppressive roles to Atrx." (PMID 37296979, 2023). "K-RAS mutation (KRAS-mt) confers tumor cell growth at lower glucose concentrations than those required by normal cells and strongly promotes tumor cell growth." (PMID 36782251, 2023). "Our results indicate that tumours with KRAS mutation tend to contain many small groups with high grey levels." (PMID 37509345, 2023). "A general enrichment of the dPITPNC1 GS was found in LUAD tumours harbouring KRAS mutations compared to those with native alleles." (PMID 37210549, 2023). "Combined targeting of this axis and KRAS effectively abrogates drug resistance, causing cell death and tumor regression." (PMID 38104151, 2023). "After three cycles, we observed radiographic tumor regression and disappearance of the KRAS variant from the corresponding cfDNA." (PMID 37685884, 2023). "The investigators demonstrated that combination treatment with AZD6244 as well as the GRB7 axis was able to synergistically suppress KRAS-mutated CRC tumor growth in the HCT116 xenograft model." (PMID 37569406, 2023). "Here, we show how KRAS-mutant tumors are dependent on IL-β provided by tumor-associated macrophages." (PMID 36980752, 2023). "The tumor Akt level, neural invasion, and KRAS mutation status were the most important determinants for overall survival." (PMID 37639911, 2023). "In conclusion, since KRAS mutation is so common in PDAC, the detection of KRAS mutation in fluid or tumor tissue can have an important impact on the diagnosis, prognosis evaluation and treatment decision of PDAC." (PMID 37304241, 2023). "A notable difference was observed in the Tumor Mutation Burden (TMB) levels across the four KRAS subtypes, with the G12D subtype displaying the lowest TMB level." (PMID 37954616, 2023). "During neoadjuvant chemotherapy, the KRAS ctDNA levels significantly decreased: at four weeks, a total of 63% of patients with KRAS-mutated tumours had detectable ctDNA, while this dropped to 19% of patients preoperatively (p = 0.0001)." (PMID 37947598, 2023). "We have found correlations between the mechanical properties (relative stiffening between normal and neoplastic ECM) of the ECM and patients’ clinical data, like age, sex, presence of protein activating mutations in BRAF and KRAS genes and tumour grade." (PMID 37500685, 2023). "Given that several excellent reviews have summarized the role of RAS signaling in oncogenesis and the advances in RAS inhibitors for anti-tumor therapy, we herein focus on KRAS mutations and summarize the promising new treatment options." (PMID 37662925, 2023). "Traditionally, all KRAS point mutations observed in human tumours were considered to mediate their transforming potential through the same effector pathways." (PMID 37627169, 2023). "Patients with a KRAS mutation had more tumor regression in surgical specimens following ChRT and longer DFS following surgery than patients with an EGFR mutation, yet, trended towards a shorter duration of OS." (PMID 37751214, 2023). "We depicted the first KRAS mutation landscape of rare tumors in a large Chinese rare tumor population and observed an overall prevalence of 8.7% of KRAS mutation, concentrated on G12D, G12V, and G13D." (PMID 36437781, 2023).